BUB1 (BUB1 mitotic checkpoint serine/threonine kinase)
Diseases named in the same sentence as BUB1 in open-access papers (continued):
Sharing a sentence is not in itself a finding about the gene and the disease.
bladder cancer (12 papers, 2012 to 2024). "In a study investigating the molecular mechanisms of chemoresistance in bladder cancer cells, upregulation of BUB1 was identified as a significant factor in GEM resistance." (PMID 38672622, 2024). "The frequency of BUB1 gene alterations in melanoma, bladder cancer, and EC was high (frequency > 5%) and the gene alterations mainly included mutations, including missense mutations, amplifications and profound deletions." (PMID 39048649, 2024). "BUB1 regulates STAT3 signalling through transcriptional activation to facilitate bladder cancer progression and proliferation." (PMID 38498903, 2024). "Low expression of BUB1 was also associated with poorer ICB outcomes in renal and bladder cancers and in treatment-naïve melanomas treated with ICB (second panel from left)." (PMID 37745716, 2023). "bub1 expression was increased in human bladder cancer (BCa), and bub1 kinase drives the progression and proliferation of BCa by regulating the transcriptional activation of STAT3 signaling." (PMID 36237324, 2022). "In in vitro analyses, BUB1 promoted the proliferation of bladder cancer cells by accelerating the G2/M transition of the cell cycle." (PMID 34884561, 2021). "The specific internal mechanism by which BUB1 regulates bladder cancer occurrence and development needs to be further studied." (PMID 34852826, 2021). "To further verify these TCGA data, we investigated the mRNA expression of BUB1 in 34 collected paired bladder cancer tissues, and the results showed that the mRNA expression of BUB1 was significantly higher in bladder cancer tissues than in normal tissues." (PMID 34852826, 2021). "To explore the correlation between BUB1 expression and the occurrence and development of bladder cancer, we conducted immunohistochemical staining for BUB1 in these bladder sections." (PMID 34852826, 2021). "In the present study, we identified and provided evidence that BUB1 has oncogenic effects on bladder cancer transformation." (PMID 34852826, 2021). "The immunohistochemical staining results for BUB1 further confirmed the role of BUB1 in the occurrence and development of bladder cancer." (PMID 34852826, 2021). "The results showed that BUB1 expression in bladder cancer was upregulated compared with that in normal bladder tissue." (PMID 34852826, 2021). "BUB1 plays a key role in chromosome arrangement during the spindle assembly checkpoint and mitosis and it promotes the initialization and development of bladder cancer by regulating the STAT3 signaling." (PMID 38053725, 2023). "We found that BUB1 expression was higher in bladder cancer in situ than in normal bladder epithelium and that BUB1 expression in papillary bladder cancer and invasive bladder cancer was significantly elevated compared with that in bladder cancer in situ and normal bladder epithelium." (PMID 34852826, 2021). "Furthermore, we collected 34 paired bladder cancer tissues from our hospital and analyzed the expression of BUB1 in these patient samples by immunohistochemical staining." (PMID 34852826, 2021). "In this study, we found that BUB1 expression was increased in human bladder cancer (BCa)." (PMID 34852826, 2021). "Conclusively, BUB1 modulates the G2/M transition to promote the proliferation of bladder cancer cells, suggesting that it could serve as a prognostic marker in NMIBC." (PMID 34884561, 2021). "In bladder cancer (BCa), weighted gene co-expression network analysis showed that BUB1 is upregulated in high-grade BCa; however, the roles of BUB1 in BCa remain unclear." (PMID 34884561, 2021). "To further explore the relationship between BUB1 and the occurrence and development of bladder cancer in vivo, we established a model of spontaneous bladder cancer in KM mice via feeding water supplemented with 0.1% BNN (N-butyl-N-(4-hydroxybutyl) nitrosamine), which induces bladder cancer." (PMID 34852826, 2021).
bladder cancer (continued). "We further divided these patients into high and low BUB1 expression groups and analyzed the correlation between BUB1 expression and several common clinicopathological features of bladder cancer (including age, sex, tumor grade, tumor size and metastasis status)." (PMID 34852826, 2021). "Interestingly, the expression of BUB1 in low-grade bladder cancer was lower than the expression of BUB1 in high-grade bladder cancer." (PMID 34852826, 2021). "Targeting BUB1 has been shown to be a promising strategy in osteosarcoma patients, where inhibition of the kinase markedly suppressed cell proliferation, migration, invasion, and induced apoptosis; in bladder cancer, BUB1 inhibition suppressed tumour progression." (PMID 38396175, 2024). "We also found that BUB1 was positively related to STAT3 based on TCGA data in the online GEPIA database (R = 0.21; P < 0.05), which further supports the hypothesis that BUB1 might regulate the progression and prognosis of bladder cancer by mediating the STAT3 signaling pathway." (PMID 34852826, 2021). "The results demonstrated that bladder cancer was successfully induced via feeding BNN-supplemented water and that BUB1 expression increased gradually with the progression of bladder cancer." (PMID 34852826, 2021). "BUB1 was found to modulate the G2/M transition to promote the proliferation of non-muscle-invasive bladder cancer cells and drove the progression and proliferation of bladder cancer by regulating the transcriptional activation of STAT3 signaling." (PMID 36787437, 2023).
melanoma (12 papers, 2008 to 2025). A malignant, usually aggressive tumor composed of atypical, neoplastic melanocytes. "BUB1 is positively correlated with the G2 markers in both melanoma and monocyte populations, p < 10−5, p < 10−4, respectively." (PMID 36527135, 2022). "BUB1 has been noted to be abnormally expressed in several cancers including gastric, colon, esophageal, breast, and melanoma." (PMID 23840955, 2013). "Its pro cancer mechanism mainly includes two aspects: on the one hand, DTL promotes the malignant progression of melanoma by reshaping the glucose metabolism process of tumor cells; On the other hand, it drives the proliferation and migration of melanoma cells via the ERK/E2F1/BUB1 signaling axis." (PMID 41409301, 2025). "The aberrant expression of BUB1 seems to have an especially strong correlation with melanoma." (PMID 23840955, 2013). "The major anticancer/antimetastatic effect of MePip-SF5 may therefore be related rather to interference with the cell cycle of the rapidly proliferating melanoma cells because Bub-1, an important negative regulator of the cell cycle, was downregulated by MePip-SF5 treatment." (PMID 37998354, 2023). "Similarly, we observed a significantly lower expression of the BUB1 gene in our cohort of canine melanomas (lFC = −1.06; padj = 0.02), in accordance with recent findings showing recurrent deletions of BUB1 in mucosal melanomas using a cross-species strategy, including human, horse, and dog samples." (PMID 31234577, 2019). "Inhibition of CDK2 in melanoma cell lines has been shown to overcome their resistance to BRAF and Hsp90 inhibitors, while BUB1 has been identified as a novel target downstream of SIRT1 in melanoma." (PMID 38023136, 2023). "The qRT-PCR and immunoblot analyses showed that tenovin-1 inhibition of SIRT1 resulted in a downregulation of BUB3, BUB1 and BUBR1 in multiple melanoma cell lines." (PMID 24743044, 2014). "Tenovin-1 treatment was found to result in a significant decrease in BUB3, BUB1 and BUBR1 proteins in melanoma cells." (PMID 24743044, 2014). "Taken together, our study has identified novel insights into SIRT1 signaling in melanoma by connecting this important protein deacetylase with spindle assembly check point proteins BUB3, BUB1 and BUBR1." (PMID 24743044, 2014). "Therefore, as the next step, we analyzed the effect of tenovin-1 on protein levels of BUB3, BUB1 and BUBR1 in all three melanoma cell lines." (PMID 24743044, 2014).
lymphoma (11 papers, 2013 to 2024). A malignant (clonal) proliferation of B- lymphocytes or T- lymphocytes which involves the lymph nodes, bone marrow and/or extranodal sites. "Previous studies have reported similar spindle structures, and demonstrated that elevated BUB1 expression in lymphoma cells causes aneuploidy through excessive activation of Aurora B kinase." (PMID 38498903, 2024). "Moreover, BUB1 overexpression was found to drive spontaneous tumorigenesis and accelerate Myc-induced lymphoma development in transgenic mice." (PMID 34852826, 2021). "Interestingly, BUB1 overexpression induces aneuploidy in lymphoma cells through Aurora B kinase (AURKB) hyperactivation, while BUB1 downregulation occurs in a subset of acute myeloid leukemia." (PMID 32781708, 2020).
pancreatic cancer (11 papers, 2013 to 2024). "We first show that high expression of Mitotic checkpoint serine/threonine kinase BUB1 in pancreatic cancer and its association with poor prognosis." (PMID 38672622, 2024). "Results also suggested that BUB1 suppresses ferroptosis in pancreatic cancer cells, and BUB1 knockdown significantly enhances the sensitivity of drug-resistant pancreatic cancer cells to ferroptosis." (PMID 38672622, 2024). "In studies conducted on pancreatic cancer cells, BUB1 was identified as a promoter of cell proliferation, migration and gemcitabine resistance." (PMID 38791174, 2024). "FDI-6 reverses olaparib-induced adaptive resistance and inhibits cell cycle progression and DNA damage repair by repressing the expression of BUB1 in pancreatic cancer." (PMID 36787437, 2023). "In this study, CD74-MIF and BUB1 were found to be potential therapeutic targets for treating pancreatic cancer." (PMID 35769782, 2022). "BUB1 can serve as a prognostic biomarker and a therapeutic target for patients with pancreatic cancer." (PMID 35769782, 2022). "We believe that our study makes a significant contribution to the literature because it was previously unclear whether BUB1 plays a key role in pancreatic cancer ferroptosis." (PMID 38672622, 2024). "BUB1 could serve as a biomarker for predicting prognosis of patients with pancreatic cancer, as it also presented robust performance in the independent dataset." (PMID 35769782, 2022). "Reduced BUB1 expression was observed in a subset of pancreatic cancer cells." (PMID 26287798, 2015). "Reduced Bub1 expression has been detected in a subset of lung, colon and pancreatic cancers." (PMID 23805780, 2013). "Furthermore, BUB1 promotes gemcitabine resistance in pancreatic cancer cells." (PMID 38672622, 2024). "Importantly, BUB1 could serve as a biomarker for predicting prognosis and a therapeutic target for treating pancreatic cancer, but this needs further experiments." (PMID 35769782, 2022). "Eight genes (BUB1, BUB1B, CCNA2, CCNB2, CDC6, CDC20, CDK1, and TTK) among 21 common network genes were correlated with worse survival of pancreatic cancer, highlighted with P-value significantly <0.05." (PMID 32117719, 2020).
lung adenocarcinoma (10 papers, 2013 to 2026). A carcinoma that arises from the lung and is characterized by the presence of malignant glandular epithelial cells. "Additionally, dysregulation of the BUB1 network has been identified as a central hub in the genomic landscape of lung adenocarcinoma." (PMID 40180891, 2025).
sarcoma (10 papers, 2020 to 2025). A usually aggressive malignant neoplasm of the soft tissue or bone. "Previous studies have linked high BUB1 expression to aneuploidy, a condition that exacerbates the development of various diseases, including human sarcoma." (PMID 40746357, 2025). "Determining the association between BUB1 levels and other clinicopathological features in sarcomas remains as a perspective." (PMID 40723917, 2025). "It has been known that BUB1 regulates mitosis; for this reason, we explored the cellular growth of sarcoma cell lines in the presence of the kinase inhibitor." (PMID 40723917, 2025). "All this evidence highlighted the participation of BUB1 expression in signaling pathways and cellular processes altered in cancer and positioned this kinase as a central molecule for malignancy in the sarcomas analyzed." (PMID 40723917, 2025). "Altogether, these findings underscore the potential of BUB1 as a therapeutic target and prognostic marker in sarcomas." (PMID 40723917, 2025). "Higher expression levels of BUB1, BUB1B, and BUB3 were found in sarcoma samples and were associated with lower overall and disease-free survival in sarcoma patients." (PMID 38473259, 2024). "Three BUB family members have been identified in patients with different types of sarcoma: BUB1, BUB1B and BUB3." (PMID 33872216, 2021). "Survival analysis revealed that the higher expression levels of BUB1, BUB1B and BUB3 were associated with lower overall and disease-free survival in patients with sarcomas." (PMID 33872216, 2021). "Finally, a correlation between high levels of BUB1 and poor overall survival in patients of all analyzed sarcomas was determined." (PMID 40723917, 2025). "The inhibition of BUB1 through targeted therapy not only represents a novel pharmacologic strategy for sarcoma treatment but may also contribute to improving patient outcomes by limiting tumor proliferation and invasion." (PMID 40723917, 2025). "Finally, overall survival analysis highlighted a strong correlation between high BUB1 expression and poorer survival rates in sarcoma patients." (PMID 40723917, 2025). "Additionally, in comparison to the normal controls, the sarcoma tissues and cells exhibited obviously high BUB1, BUB1B, and BUB3 expression." (PMID 36439516, 2022). "In addition, using the Kaplan-Meier Plotter and GEPIA databases, we determined that the overall and disease-free survival of sarcoma patients were significantly lower in patients with overexpressed BUB1 and BUB1B." (PMID 33872216, 2021). "Finally, the clinical utility of BUB1 kinase expression in sarcomas was evident." (PMID 40723917, 2025). "Moreover, Sun and Cols reported that in this type of sarcoma high levels of BUB1 could be regulated by the family of homology 60A (FAM60A) protein." (PMID 40723917, 2025). "BUB1 inhibition reduced the phosphorylation of AKT and H2A proteins, precluded cell proliferation, and inhibited colony formation in sarcoma cells." (PMID 40723917, 2025). "We found that the expression levels of BUB1, BUB1B and BUB3 were higher in sarcoma samples and cell lines than in normal controls." (PMID 33872216, 2021). "In the present study, analysis using the Oncomine and GEPIA datasets revealed that the expression of BUB1 and BUB1B were higher in human sarcomas than in normal tissues." (PMID 33872216, 2021). "This study implies that BUB1, BUB1B and BUB3 are potential treatment targets for patients with sarcomas and are new biomarkers for the prognosis of sarcomas." (PMID 33872216, 2021). "Using sarcoma cell lines and non-tumoral mesenchymal cells, the gene expression and protein levels of BUB1 were measured." (PMID 40723917, 2025). "BUB1, BUB1B, and BUB3 may serve as a future potential treatment targets and prognostic biomarkers for patients with sarcomas." (PMID 38473259, 2024). "Our results indicated that BUB1, BUB1B and BUB3 may serve as oncogenes in sarcomas and have significant prognostic values." (PMID 33872216, 2021).
sarcoma (continued). "Notably, the expressions of BUB1 and BUB1B are significantly higher in sarcomas compared to normal tissues." (PMID 33872216, 2021).
breast tumors (9 papers, 2011 to 2024). "We examined the expression of BUB1 in breast tumors (N = 202) and compared with normal breast tissues (N = 15)." (PMID 38863037, 2024). "Immunohistochemical analysis revealed a significantly high BUB1 protein expression in breast tumors compared to normal breast tissue." (PMID 38863037, 2024). "Three of the four genes were overexpressed in breast tumors arising in younger women compared to older women: BUB1 (Fold Change 1.67, p = 0.029), KRT5 (Fold Change 1.56, p = 0.002), and MYCN (Fold Change = 1.16, p = 0.027)." (PMID 25999348, 2015). "Analysis of these miR-10b* targets by immunohistochemistry (IHC) in ten matched breast tumour and peritumoural tissues (from the cohort analysed by microarray miR profiling) showed remarkable increased staining of BUB1, PLK1 and CCNA2 in the tumour tissues." (PMID 23125021, 2012). "Regarding to the clinical relevance of our results, low expression levels of βArr1 were inversely correlated with CDC45, BUB1, CCNB1, and CCNB2 genes compared to normal tissue samples while positively correlated with poorer prognosis in breast tumours." (PMID 33452359, 2021). "The PR gene, PGR, and 3 other genes (GATA3, STC2 and GLI3) are increased in their expression, whereas the expression of 6 genes (AURKA, BUB1, CDC20, MKI67, HJURP, and CENPA) is decreased in PR-positive breast tumors." (PMID 22022496, 2011). "NHW women with Her2 + breast tumors significantly overexpress TTK, TBK1, Nek2, BUB1, and SGOI." (PMID 36494865, 2022). "TCGA data analysis also indicates the clinical relevance of our results, the low expression levels of βArr1 are inversely correlated with CDC45, BUB1, CCNB1, and CCNB2 genes compared to normal tissue samples while positively correlated with poorer prognosis in breast tumours." (PMID 33452359, 2021).
endometrial carcinoma (9 papers, 2011 to 2026). A malignant tumor arising from the epithelium that lines the cavity of the uterine body. "This study aimed to evaluate the expression and clinical significance of budding uninhibited by benzimidazole 1 (BUB1) and BUB1 mitotic checkpoint serine/threonine kinase B (BUB1B) in endometrial carcinoma (EC)." (PMID 39048649, 2024). "Our findings corroborate previous studies that have implicated TPX2, BUB1, and ESPL1 in the development and progression of endometrial cancer." (PMID 39596419, 2024). "The expression of microRNA (miR)-524-5p reduced the migration and invasion of Ishikawa endometrial carcinoma (EC) cells, while decreasing BUB1, BUB1B, CCNA2, and CDCA8 expression." (PMID 37853361, 2023). "In addition, BUB1 played an active role in promoting the proliferation of Human endometrial epithelial cells and endometrial cancer Ishikawa cells." (PMID 41491570, 2026). "The focus of the immunohistochemical experiments was to investigate expression of BUB1 and BUB1B in endometrial cancer and normal endometrial tissue, and thus only 20 cases were selected." (PMID 39048649, 2024).